CDK4 (cyclin dependent kinase 4)
Diseases named in the same sentence as CDK4 in open-access papers (continued):
Sharing a sentence is not in itself a finding about the gene and the disease.
tumor (continued). "The decreased expression of CDK4, CDK6 which were directly inhibited by p16, along with the down-regulated expression of Cyclin D1, E2F1 and pRb confirmed the anti-tumor function of miR-877-3p was the due to p16 activation." (PMID 27429046, 2016). "We found that either cyclin D1 or CDK4 could not only reverse the inhibitory phenotype produced by Tspan5 but also promote the cell growth further as compared to the basal control, suggesting that cyclin D1/CDK4 have a dominant role in mediating the suppression of tumour growth by Tspan5 in GC." (PMID 27223087, 2016). "The statistical analysis of clinicopathological parameters showed a correlation between CDK4 and PRMT5 co-expression level and tumor size or tumor stage (P < 0.05)." (PMID 27708221, 2016). "The protein expression levels of cyclin D1, CDK4, cyclin E, CDK2, and Ki-67, a biological tumor marker that indicates changes in tumor proliferation, were reduced in the shVCP-transfected HCT116 cells, and increased in the lenti-VCP transfected RKO cells." (PMID 27344168, 2016). "We found that tumor cells and patient-derived xenografts (PDXs) respond more strongly to a CDK inhibitor when they express high levels of CDK4 but exhibit resistance to the CDK inhibitor when they express high levels of p16ink4a." (PMID 26528855, 2015). "In addition to EMT regulation, the well-known property of miR-34a is its tumor suppressor function via inducing cell cycle arrest and apoptosis in various cancer types by targeting several molecules crucial for sustaining tumor growth such as CDK4/6, MET, HDAC1, E2F3 and Bcl-2." (PMID 25614041, 2015). "Meriolin 3 prevents phosphorylation of CDK1, CDK4 and CDK9 sites, and potently inhibits tumour growth in mouse xenograft models." (PMID 25625291, 2015). "SNP array identified frequent shared copy number events in all three tumor regions including FGFR1 amplification at chromosome 8p11.23 and classical CDK4, HMGA2 and MDM2 amplification at chromosome 12q13-15 region and deletion of TP53BP1 at chromosome 15q15." (PMID 26643872, 2015). "In tumours with functional RB1, inhibition of CDK4 and CDK6 activity has a significant suppressive effect on cell proliferation." (PMID 25896606, 2015). "As expected, there was a down regulation of cellular proliferation molecules CDK1, CDK2, CDK4, CDK6, Cyclin D1, Cyclin E and Cyclin B1 and upregulation of p16 and p21 in the xenograft tumor tissues by IHC." (PMID 26590805, 2015). "In every tumor that exhibited EGFR, PDGFRA, NTRK1, MDM2, MDM4, or CDK4 amplification, the increased copy number was contained within, or contained translocations into, a suspect chromothriptic region." (PMID 26328271, 2015). "We found that levels of molecules cyclin D1, CDK4, E2F1 and PCNA were increased significantly in the tumor lysates of metformin administered mice as compared to control, while p21 level was diminished." (PMID 26484566, 2015). "Immunohistochemical examination indicates that the tumor cells were diffusely positive for Factor VIII, Fli-1, CDK4, INI-1, MDM2, vimentin, focally positive for AE1/AE3, CD31 and negative for actin-sm, CD34, desmin, myoD1 and S-100." (PMID 26315812, 2015). "On the basis of the alterations identified in the tumor samples, a second targeted agent from a list of MEK, CDK4/6, FGFR, PI3K, and c-MET inhibitors will be added to the regimen." (PMID 25344914, 2014). "Q-PCR of the tumor specimens revealed varying levels of MDM2 and CDK4 amplification, with 44 cases (91.7%) and 46 cases (95.8%) showing positive amplification of CDK4 and MDM2 genes, respectively." (PMID 25121597, 2014).
tumor (continued). "The results show that cdk4 levels altered SME gene expression in normal mammary epithelial cells, but with a different pattern than seen in tumor-derived cell lines." (PMID 24848372, 2014). "As in MDA-MB-468 and MCF-7 tumor cells, increases in the levels of AKR1C-family transcripts were seen in the cdk4-transfected normal breast cells." (PMID 24848372, 2014). "Because miR-195 is involved in repression of cell cycle accelerators (CCND1, CCNE1, CDK4, CDK6, and E2F3) and anti-apoptotic factors (BCL2, BCL2L2, and BIRC5), miR-195 functions as a tumor suppressor miRNA in various types of human cancers." (PMID 25364765, 2014). "While blocking STAT3 signaling can induce apoptosis and inhibit angiogenesis in tumor cells, low levels of STAT3 can still stimulate proliferation by inducing the expression of CyclinD1 and CDK4." (PMID 25007077, 2014). "To further explore the mechanism of EESP’s anti-tumor activity, we performed RT-PCR and IHS analyses to respectively examine the mRNA and protein expression of Bcl-2, Bax, Cyclin D1, CDK4, VEGF-A and VEGFR-2 in CRC mice." (PMID 23800091, 2013). "In this region, there are important oncogenes such as CHOP (DDIT3), GLI, MDM2, CDK4, SAS, HMGA2, but also the HOXC locus, involved in development and tumor progression." (PMID 24085196, 2013). "These tumor suppressive effects of miR-34a are mediated by changes in a number of target mRNAs including MYCN, CDK4, cyclin D1, SIRT1 and Bcl-2." (PMID 22629428, 2012). "Immunohistochemical staining of tumor sections revealed that the proportions of Ki-67-positive cells and the expression of CDK2 and CDK4 were increased in mice co-injected with 4T1 cells and M2-Mφs." (PMID 22616919, 2012). "The molecular effects of 20mg/kg or 40mg/kg 17-AAG on the transgenic MMTV-NEU-NT tumours included the induction of the co-chaperone HSP72 and depletion of client proteins NEU/HER2, C-RAF and CDK4." (PMID 22621282, 2012). "Ectopic expression of PRDM5 inhibited tumor cell clonogenicity, at least partially through antagonizing WNT/β-catenin signaling and oncogene expression such as CDK4, TWIST1, and MDM2." (PMID 22087297, 2011). "Among this cluster of adjacent genes is CDK4, a cyclin-dependent kinase that is an inhibitor of the RB1 tumor suppressor and known target of CDKN2A's p16 product." (PMID 21489305, 2011). "The in vitro molecular data showed that tumor cells that had been in contact with ADSC-CM were in a resting state (G0/G1), and down regulated CDK4 and cyclinD1." (PMID 19609435, 2009). "Our data demonstrate a defined and specific inhibition of tumor cell proliferation through CKIA and CKIB by inhibition of the Cdk4/pRb/E2F pathway emphasizing potential therapeutic benefit of CKIA and CKIB." (PMID 19551155, 2009). "Two high-risk genes have been identified: the cell cycle regulator CDKN2A on chromosomal band 9p21 and the cyclin-dependent kinase-4 (CDK4) on chromosomal band 12p14, the products of which are known to be components of potent tumour-suppression pathway." (PMID 18612309, 2008). "These concerns have been fuelled by RNA interference and knockout mice studies, indicating that functional redundancy may exist between different Cdks, with the loss of Cdk2 alone failing to inhibit tumour cell proliferation, and the loss of both Cdk4 and Cdk6 not preventing cell cycling." (PMID 17179992, 2007). "CDK4 and JUND are examples of genes, where both the gene expression and protein expression is consistently increased in tumours compared to normal urothelium." (PMID 16265353, 2005). "Combination therapy with endocrine therapy and a CDK4/6 inhibitor resulted in tumor regression without new metastases." (PMID 41913901, 2026). "Furthermore, dual CDK4/6 and CDK7 inhibition stimulates immune-related signaling and cytokine production in cancer cells, promoting anti-tumor immune responses within the tumor microenvironment." (PMID 40794455, 2025).
tumor (continued). "Notably, at low doses, GDC-9545 induces tumor regression in both wild-type ERα tumor models and Y537S ERα mutant PDX models, either alone or in combination with a CDK4/6 inhibitor." (PMID 40641933, 2025). "It has demonstrated robust efficacy in human tumor xenografts, and combining STX-478 with other treatments such as fulvestrant and CDK4/6 inhibitors has provided durable tumor regression without substantial side effects." (PMID 39808497, 2025). "The results of several studies suggest that, apart from their direct effect on tumor cells, CDK4/6is influence immune cells in the TME, including the suppression of regulatory T cell proliferation and enhanced activation of tumor-infiltrating lymphocytes (TILs)." (PMID 39955556, 2025). "Given that both CDK4/6 and DUB3 contribute to tumor progression in HCC by stabilizing YAP1, we hypothesized that DUB3 might serve as a linker between CDK4/6 and YAP1." (PMID 40307228, 2025). "In this study, the expression of the tumor-suppressive CDK inhibitor p27 was increased, and the expression of oncogenic CDK2 and CDK4; cyclins (A, D, and E); and pRb was decreased by galectin-1 knockdown and miR-22-3p overexpression in primary hormone receptor-positive breast cancer cells." (PMID 39996781, 2025). "MDM2 and CDK4 amplification is a potential therapeutic target in these tumours with ongoing Phase I and II trials of CDK4 and/or MDM2 inhibitors, but there are no established treatment options developed yet based on these genetic alterations." (PMID 40144205, 2025). "Oncogenes with expression scaling with amplification, such as RAC1 and CDK4, were less methylated when amplified (P = 1.53 × 10−5 and 5.63 × 10−4, respectively; Mann–Whitney U-test) compared to non-amplified tumor regions." (PMID 40931149, 2025). "The main outcomes were differences in circulating tumor DNA profiles and use of phosphoinositide 3-kinase (PI3K), mammalian target of rapamycin (mTOR), and cyclin-dependent kinase 4/6 (CDK4/6) inhibitors between Black and White patients with metastatic breast cancer." (PMID 40009379, 2025). "Inhibition of CDK4 downregulates SPOP, stabilising PD-L1 on the tumour surface." (PMID 40563591, 2025). "By comparing the cfDNA WGS with sequencing on the primary tumor and metastasis at the time of relapse, we demonstrated a high degree of concordance in the identification of key genomic alterations, including MYCN and CDK4/MDM2 amplifications." (PMID 40386554, 2025). "Upon disease progression, CDK4/6i therapy is typically discontinued, often resulting in aggressive tumor regrowth and a lack of effective second-line treatment options." (PMID 39605351, 2025). "Inactivation of the SMARCA4 gene, which encodes BRG1 protein, increases tumor invasiveness and affects sensitivity to conventional platinum-based chemotherapeutic agents but may increase tumor sensitivity to EZH2 inhibitors, CDK4/6 inhibitors." (PMID 40661782, 2025). "Most importantly, we found that the combination of NEK2 and CDK4/6 inhibition decreases tumor volume in vivo in three different models without inducing overt toxicity as indicated by stable mouse weights." (PMID 39826695, 2025). "A CDK4 immunohistochemical stain on a metastatic lung tissue sample confirmed CDK4 overexpression in the tumor but not in the surrounding non-neoplastic lung parenchyma; Retinoblastoma protein was intact (data not shown)." (PMID 40379813, 2025). "For instance, the dysregulation of the CDKN2A-CDK4/6 axis in LC4 cells makes the 2D model particularly suited for preclinical testing of CDK4/6 inhibitors, allowing focused analysis of tumor cell behavior in a controlled environment free from stromal influences." (PMID 40431665, 2025). "Similarly, tumor tissue from mice treated with AT56 displayed decreased expression of c-myc, CDK4 and vimentin, and increased expression of cleaved PARP and Bax." (PMID 39706989, 2025).
tumor (continued). "Mechanistically, CDK4/6i enhances the accumulation and activation of M1 TAMs and promotes the M2 to M1 polarization via augmented interaction of the macrophage migration inhibitory factor (MIF)-CD44/CD74 axis between tumor cells and macrophages." (PMID 41082324, 2025). "Moreover, it is feasible that cotargeting of CDK4/6 and NEK2 will effectively induce intolerable mitotic defects in tumor cells, while sparing normal cells." (PMID 39826695, 2025). "In addition, IHC analysis of the tumor tissues confirmed that DARS2 knockdown considerably reduced PINK1 and CDK4 expressions, which were partially restored upon PINK1 overexpression, consistent with our earlier findings." (PMID 39990673, 2025). "To assess whether the cytotoxic effects of the combined drug treatment are dependent on PML in vivo, we established tumor-bearing nude mice using either control or PML gene-edited MOLM-13 cells and administered CDK4/6i and ATRA." (PMID 40753178, 2025). "Collectively, our study uncovers a novel oncogenic role of the CDK4/6‐DUB3 pathway, which promotes YAP1 stabilization and tumor‐promoting function, highlighting that targeting CDK4/6 offers a potential therapeutic strategy for CRC with aberrantly upregulated DUB3 and YAP1." (PMID 39968498, 2025). "While tumor tissues displayed medium or strong CDK4 IHC staining, normal liver tissue displayed negative or moderate staining." (PMID 38231074, 2025). "Preclinical data have shown that in tumor‐bearing mouse models that are either sensitive or insensitive to CDK4/6 inhibitors, trilaciclib does not interfere with the inhibitory effects of chemotherapy on tumor growth." (PMID 40232146, 2025). "These were assayed for tumour-initiating potential and organoid-forming ability, as well as for transcriptional regulators of the hybrid EMT state by RNA and ATAC-sequencing, and their regulation by the Wnt/ERK/CDK4/6 signalling pathway." (PMID 40764669, 2025). "Combined inavolisib and CDK4/6 inhibition targets complementary tumor vulnerabilities—sustained PI3K signaling and aberrant cell-cycle progression—thereby addressing key resistance nodes and modulating the tumor microenvironment." (PMID 41280894, 2025). "Although some previous reviews have focused on CDK4/6is and tumor immunity, none have clearly elucidated in which aspects CDK4/6is specifically exhibit “duality”." (PMID 41463246, 2025). "Similarly, tumor tissue from mice bearing sh-PTGDS cells displayed decreased expression level of c-myc, CDK4, vimentin and Ki67, and increased expression level of Bax and cleaved PARP." (PMID 39706989, 2025). "The G1T28‐04 clinical study conducted in patients with TNBC demonstrated that trilaciclib exhibits comparable efficacy regardless of CDK4/6 dependency, indicating that it does not interfere with the cytotoxic effects of chemotherapy on tumor cells." (PMID 40232146, 2025). "Of note, terminal exhausted CD8+ T cells accumulated over time in the CDK4/6i and anti‐PD‐1 priming groups but not in the C‐P regimen, which led to the most extensive and durable tumor regression in the orthotopic and subcutaneous MOC2 models." (PMID 40936164, 2025). "In view of the lack of treatment response, a CDK4/6 inhibitor–based endocrine regimen was initiated, achieving substantial tumor regression and prolonged disease control." (PMID 41551151, 2025). "As indirect evidence, CDK4/6 inhibitors can suppress RB1 expression, and antagonize the anti‐tumor effects of thiopurine (i.e., 6MP, azathioprine, and thioguanosine), which may be induced by coactivated NUDT15 expression." (PMID 40904703, 2025).
tumor (continued). "Furthermore, chromosome 12q amplicons containing CDK4 (12q14.1) and MDM2 (12q15) were detected both in the cfDNA and the tumor tissues, consistent with previous findings associating these co-amplifications with poor prognosis in patients with NB." (PMID 40386554, 2025). "Additionally, it markedly reduces the expression levels of cyclin-dependent 1 (cyclin D1) and cyclin-dependent kinase 4 (CDK4), leading to significant suppression of tumor growth in mice." (PMID 40276599, 2025). "Indeed, the addition of anti-PD-L1 therapy to CDK4/6 and MEK inhibitors greatly increased the survival of mice bearing de novo MPNSTs, prolonged tumor regression, and cured ~10% of treated animals." (PMID 40723291, 2025). "By simultaneously inhibiting both CDK4/6 and CDK2, this approach maximizes tumor growth inhibition." (PMID 40243688, 2025). "Interestingly, aberrant upregulation of CDK4 and cyclin D is commonly observed in CRC with enhanced dysplasia, correlating with increased tumor cell proliferation." (PMID 39968498, 2025). "Furthermore, the combination drug decreased the mRNA expression levels of downstream c-Myc targets, including CDK4, PABPC1, ATF4, BCL2L12, and HMGA 31, in MDA-MB-231 and BT-549 cells, which are important effectors of c-Myc inhibition-induced tumor suppression." (PMID 41281757, 2025). "Given the known immunomodulatory properties of CDK4/6 inhibitors, additional studies in immunocompetent models are conducting to assess the impact of AU2–94 on immune cell populations and its additional influence on anti-tumour immunity." (PMID 40478388, 2025). "CDK4/6 inhibitors (e.g., Abemaciclib) enhance immunogenicity by increasing MHC-I and tumor antigen expression while suppressing regulatory T cell (Treg) proliferation, resulting in a higher CD8+/Treg ratio and improved synergy with PD-1 blockade, ultimately extending survival." (PMID 40666508, 2025). "CDK4/6is may potentially act as an ICD inducer, both enhancing anti-tumor immunity and generating a long-lasting anti-proliferative protective immune response." (PMID 41463246, 2025). "A preclinical study published in 2023 investigated the effects of targeting CDK4/6, MEK and PD‐L1 in MPNST and found that CDK4/6 and MEK inhibitors induced an immune response and anti‐tumor activity, which in turn enhanced the effect of anti‐PD‐L1 immune checkpoint blockade in MPNST." (PMID 41272396, 2025). "Gli is reported to be commonly coamplified with MDM2 and CDK4, and Gli-mediated upregulation of the Hedgehog signaling pathway is enriched in dedifferentiated adipose progenitor cells and DDLPS tumor cells, resulting in undesirable immune cell infiltration of the tumor." (PMID 39723387, 2024). "Therefore, our experimental results indicate that the exon 2 skipping AS event of CDK4 in CRC, while weakening tumor cell proliferation, significantly enhances cell migration." (PMID 39004679, 2024). "Given the roles of the TAM receptors in promoting the creation of an immunosuppressive tumor microenvironment (TME), we further demonstrate that the combination of CDK4/6 inhibitor abemaciclib and sitravatinib modifies the immune landscape of TNBC to favor immune checkpoint blockade." (PMID 38927958, 2024). "MMP11 was highly expressed in the cancerous ductal epithelium and might act as a tumor promoter in PDAC, stimulating cyclin-dependent kinase 4 and cyclin D1." (PMID 38572434, 2024). "Molecular landscapes of the tumor tissues before and after Palbociclib treatment were obtained by IHC and WES for investigating potential responsive and drug-resistant markers indicating the administration or withdrawal of CDK4/6 inhibitor." (PMID 38369555, 2024). "We next sought to determine the extent to which the senescence phenotype induced by INX-315 treatment of CDK4/6i–resistant tumors was similar to, or distinct from, CDK4/6i–induced senescence in non-resistant tumor cells." (PMID 38047585, 2024).